PVR (PVR cell adhesion molecule)
Diseases named in the same sentence as PVR in open-access papers (continued):
Sharing a sentence is not in itself a finding about the gene and the disease.
tumor (continued). "CD8+ T cells or DX5+ (CD49b) NK cells isolated from CD226-deficient mice are less cytotoxic to PVR-expressing tumor cells but not to PVR-negative tumor cells." (PMID 33670993, 2021). "However, during tumor formation, malignant cells highly express PVR, which can bind to DNAM-1 and CD96 activating the antitumor effects of NK cells." (PMID 32774149, 2020). "Specifically, tumor cells expressed PD-L1 (encoded by CD274) and PVR transcripts, which could transmit inhibitory signals to PD-1 (encoded by PDCD1 gene) and TIGIT on T cells, respectively." (PMID 32460812, 2020). "Although PVR overexpression was correlated with poor prognosis in multiple studies, we found a significant moderate positive correlation between PVR expression and immune cell density in tumor nests including CD45+ and CD8+ cells." (PMID 32506804, 2020). "2B4 might direct NK cell response against/towards hematopoietic cells by binding CD48 molecule, while DNAM-1 against/towards DCs, endothelial cells or specific tumour histotype by binding its ligands, poliovirus receptor (PVR) and Nectin-2." (PMID 32204481, 2020). "TIGIT/PVR ligation could disrupt the granule polarization and cytotoxicity of NK cells and suppress the anti-virus and anti-tumor activity of CD8+ T cells." (PMID 32894141, 2020). "However, several studies have observed the shedding of MIC A/B (NKG2D ligand) and CD155 (also known as poliovirus receptor (PVR)) (DNAM-1 ligand) from tumour cells, which prevents NK cell activation and leads to NK cell hyporesponsiveness." (PMID 32640575, 2020). "In addition, the anti-tumor effects of blocking TIGIT by the antibody or recombinant PVR protein were investigated, and the anti-tumor effects of anti-TIGIT through tumor intrinsic TIGIT were also studied." (PMID 30555485, 2018). "Interestingly, a number of additional studies report a prognostic relevance for PVR in several tumor entities." (PMID 29855615, 2018). "Although the PVR protein slightly increased the proportion of CD8+ T cells in the tumor site compared with α-TIGIT, the PVR protein could significantly inhibit the growth of CT26 tumors." (PMID 30555485, 2018). "Whether PVR proteins exert tumor inhibition by interacting with other cells types remains investigated." (PMID 30555485, 2018). "The mechanism underlying the enhanced tumor cell killing may involve the increased expression of MICA, MICB, PVR, and Nectin-2 proteins on MM cells and the ligands of the activating receptors, NKG2D and DNAM-1." (PMID 27992381, 2017). "Treatment of different tumor cell types with epigenetic drugs, like histone deacetylase inhibitors (HDACi) and DNA-methyltransferase inhibitors (DNMTi), leads to the upregulation of NKG2DLs and PVR surface levels, although it downregulates B7-H6 expression." (PMID 28993779, 2017). "It would be of interest to understand whether the high expression of PVR in MMECs might improve migration of monocytes, which in the tumor microenvironment tend to differentiate into macrophages and acquire a M2 tumor-promoting functional polarization." (PMID 28456791, 2017). "We found a significant upregulation of MICA and PVR/CD155 mRNA and cell surface expression by lenalidomide and pomalidomide; accordingly, NK-cell degranulation was enhanced upon interaction with IMiDs-treated tumor cells." (PMID 26269456, 2015). "Notably, PVR is overexpressed in several tumor cells types and can be induced by Ras activation and genotoxic stress." (PMID 26347741, 2015). "Indeed, although data in NB are missing, PVR has been described as a positive regulator of cancer progression, since it is capable of enhancing tumor cell invasiveness and migration." (PMID 24575100, 2014). "Moreover, several studied indicated that most tumor cells including CSC constitutively express levels of PVR higher than the normal counterparts." (PMID 24575100, 2014).
tumor (continued). "The relative increase in active signal receipt via CD96 may represent compensatory means of tumor immune evasion as cancer cells, CAFs, TAMs, DCs, and mast cells were all found to express PVR and NECTIN1 within our dataset, both of which are capable of inducing immunosuppression in CD8+ T cells." (PMID 39811671, 2025). "Tumor co-culture in the presence of isotype control antibodies decreased the frequency of CD107a+ NK cells upon restimulation with K562 cells (37 ± 5% for PVR− (p = 0.004) and 19 ± 8% PVR+ (p < 0.0001)) with a larger decrease with PVR+-K562 cells compared to PVR− cells (p = 0.005)." (PMID 37345049, 2023). "Moreover, PVR expression was correlated with the presence of EMP, which indicates the presence of metastatic lesions, bone marrow plasma cells, and β2-microglobulin levels that are associated with tumor burden." (PMID 35625835, 2022). "Moreover, azelnidipine could not only block the TIGIT/PVR pathway, but also reduce the expression of PVR, which may further enhance the anti-tumor effects." (PMID 34068552, 2021). "Also, high affinity PVR mutants might be used in combination with multispecific drugs targeting multiple immune pathways to improve the anti-tumor effects." (PMID 33557880, 2021). "Furthermore, blocking TIGIT/PVR interaction with antibodies could induce anti-tumor effects by promoting tumor infiltration and restoring CD8+ T cell function." (PMID 34659197, 2021). "We reported that blockade of TIGIT/PVR by peptide could elicit strong tumor tissue penetration ability and anti-tumor immune response, even in anti-programmed cell death protein 1 (PD-1) resistant tumor model." (PMID 33557880, 2021). "Quite different from that, liothyronine could exert anti-tumor effects by TIGIT/PVR blockade." (PMID 32894141, 2020). "To confirm whether TIGIT could be considered as the target for immunotherapy, we observed that TIGIT blockade using antibody or recombinant mouse PVR protein could also suppress tumor growth, augment tumor-infiltrating lymphocytes and boost anti-tumor immune response in CT26 mice model." (PMID 30555485, 2018). "Moreover, PVR expression might directly favor the function of MMECs thus contributing to the formation of the complex architecture of tumor vasculature." (PMID 28456791, 2017). "Thus, further studies are required to understand whether the immunological favorable effects of PVR up-regulation might balance the induction of a more aggressive tumor phenotype." (PMID 24575100, 2014). "Thus, CD155/PVR/Necl-5 has a key role in tumor cell invasion and migration." (PMID 23833639, 2013). "It binds several nectin/nectin-like ligands, including PVR (CD155), PVRL2 (CD112), PVRL3 (Nectin-3, CD113), and PVRL4 (Nectin-4), all commonly expressed by tumor cells and APCs." (PMID 41486149, 2026). "A study found that TIGIT expression on activated NK cells enhances their anti-tumor function; however, chronic TIGIT engagement by its ligand PVR induces dysfunction." (PMID 40567374, 2025). "Collectively, these findings support the coordinated expression of the TIGIT/PVR and PD-1/PD-L1 pathways in ESCC tumor tissues and identify high expression of TIGIT/PVR as a poor prognostic marker in patients with ESCC." (PMID 39847233, 2025). "These receptors bind to CD155 (Nexl-5 or PVR) and CD112 (Nectin-2), two ligands ubiquitously expressed at low levels and often found elevated on tumor cells." (PMID 40299429, 2025). "Hemin, another small molecule that can interact with TIGIT/PVR, was developed based on virtual molecular docking and cell-based closure assays, and can interact with TIGIT/PVR and enhance anti-tumor CD8+ T cell killing activity." (PMID 40890162, 2025). "KIR2DL5 and KIR3DL3 recognize the overexpressed immunoregulatory molecules PVR (CD155) and HHLA2 on tumor cell surfaces, forming immunosuppressive synaptic structures." (PMID 41020039, 2025).
tumor (continued). "Poliovirus receptor (PVR, CD155) and CD112 are ligands expressed on tumor cells that interact with immune receptors, influencing immune suppression and activation." (PMID 40567374, 2025). "TIGIT ligands (PVR, NECTIN2, NECTIN3) were predominantly expressed on tumor cells, while LAG3 ligands (H2-AB1, H2-AA, H2-EB1) were mainly expressed on macrophages and DCs." (PMID 40027748, 2025). "In our study, we had a look at PVR and PVRL2 on the tumour cell side and TIGIT and DNAM-1 on the immune effector cell side." (PMID 40317320, 2025). "As an IC receptor within the IgSF, TIGIT interacts with ligands such as CD155 (PVR or Nectin-5), CD113 (PVRL3 or Nectin-3), CD112 (PVRL2 or Nectin-2) and PVRL4 (Nectin-4) to suppress T cell activity, facilitating tumour evasion of immune surveillance." (PMID 40994140, 2025). "For example, how Plac1 expression enhances caveolae‐related gene upregulation, and how Plac1+ tumor cells secrete higher concentrations of CXCL11 and express higher levels of PVR." (PMID 40056047, 2025). "TIGIT interacts with CD155 (poliovirus receptor, PVR, or NECL-5) on the surface of antigen-presenting cells or tumor cells and inhibits the anti-tumor response of T cells and NK cells." (PMID 40510353, 2025). "In the meantime, Plac1+ tumor cells shape a Treg‐related immunosuppressive microenvironment via CXCL11/CXCR3 and PVR/TIGIT, which in turn activates the tumorigenic signaling of Plac1+ tumor cells via LTA/LTBR and forms a reciprocal protumor loop." (PMID 40056047, 2025). "TIGIT interacts with its ligands, CD155 (PVR) and CD112 (Nectin-2), which are often overexpressed on tumor cells and antigen-presenting cells (APCs) within the TME." (PMID 40567374, 2025). "It competes with the co-stimulatory receptor CD226 (DNAM-1) for binding to shared ligands CD155 (PVR) and CD112 (PVRL2) on antigen-presenting cells and tumor cells." (PMID 40777027, 2025). "The primary ligands for DNAM‐1 include the poliovirus receptor (PVR) and Nectin‐2 (CD112), both of which are upregulated on the surface of various tumor cells and in response to cellular stress." (PMID 40959206, 2025). "CD96 belongs to the immunoglobulin superfamily and acts as a co-inhibitory receptor that competes with the co-stimulatory receptor CD226 for the shared ligands CD155 (PVR) and CD211 (NECTIN1), both of which are expressed on tumor and myeloid cells." (PMID 39811671, 2025). "In particular, two main ligands have been identified for TIGIT: CD112 (Nectin-2) and CD155 (poliovirus receptor, PVR), which are broadly expressed on antigen-presenting cells (APCs) and tumor cells." (PMID 40508202, 2025). "Then, it is revealed that Plac1+ tumor cells recruit CD4+ T cells via CXCL11/CXCR3 and induce Treg differentiation via PVR/TIGIT, which in turn activates the tumorigenic signaling of Plac1+ tumor cells via LTA/LTBR and forms a reciprocal protumor loop." (PMID 40056047, 2025). "PDL1 (CD274) - PD1 and TIGIT - CD155 (PVR) are common immune checkpoint pathways in tumors, through which tumor cells can inhibit the function of T cells by expressing CD274 and PVR." (PMID 40110547, 2025). "DNAM1/CD226 is a potent activating receptor that has been shown to recognize two ligands overexpressed by tumor cells, namely PVR/CD155 which is considered as the main ligand and Nectin2/CD112." (PMID 39179536, 2024). "Coincidentally, they are both ligands for TIGIT, and the expression of PVR and NECTIN2 is strongly correlated with epithelial and endothelial cells, and are more expressed in tumor tissues than in normal tissues." (PMID 39120585, 2024). "Running the ESTIMATE tool on bulk RNA-seq data from the TCGA-LUAD cohort, we calculated the level of tumor immune infiltration and found that high expression of NECTIN2 and PVR genes inhibited immune cell infiltration levels." (PMID 39474422, 2024). "NLRP1 is also significantly associated with most immune‐stimulating genes except for CD276, HHLA2, NTSE, PVR, TNFSF18 and UNBP1 in the HNSC‐excluded tumours." (PMID 39318060, 2024).
tumor (continued). "Another activating receptor involved in NK cell-mediated tumor cell killing is DNAM-1, which recognizes Nectin-2 (Nec-2, CD112) and the poliovirus receptor (PVR, CD155) ligands." (PMID 38731936, 2024). "Among immunostimulators, CD276, PVR, TNFRSF14, TNFRSF25 and TNFSF9 were also negatively correlated with LAMP3 expression in some tumours." (PMID 38146591, 2024). "Expression of PVR, the DNAM-1 ligand, was significantly increased on tumours and DNAM-1 mediated NK cell lysis of primary tumour tissue was observed in vitro." (PMID 39835114, 2024). "This review article will focus on PVRL2 and PVR, which play vital roles in the DNAM1 axis, from the viewpoint of tumor immunity." (PMID 39156900, 2024). "In the past, TIGIT expressed on human NK cells was shown to bind to PVR and PVRL2 and inhibit tumor killing by NK cells." (PMID 39156900, 2024). "Of note, the activated, tumour-experienced BMDCs generated by this system also expressed OX40L and PVR, resembling the phenotype of tumour-retained CCR7+ DC in vivo." (PMID 38267413, 2024). "Recombinant nonpathogenic polio-rhinovirus chimeras (PVSRIPO) recognize the poliovirus receptor (PVR) CD155, which is widely expressed in tumor cells and major components of the tumor microenvironment (TME) in solid tumors." (PMID 38167076, 2024). "In PM1, CD226 was expressed in CD27+ CD4+ and CD4+ Memory subpopulations, and corresponding ligands in tumor cells were TIGB2, NECTIN2 and PVR." (PMID 38528036, 2024). "In contrast to the lepidic pattern, the solid pattern exhibited increased significance of two additional receptor-ligand interactions, PDCD1-CD274 (PD1-PDL1) and PVR-TIGIT, between tumor cells and T cells." (PMID 39474422, 2024). "Performing cell-to-cell interaction and ligand-receptor analyses on spatial transcriptomics data they identified TIGIT expression on T and NK cells correlating with the expression of its ligands PVR and PVRL2 on myeloid and tumor cells." (PMID 38817612, 2024). "Subsequently, our flow cytometry results revealed that PVR, NECTIN2 epithelial cells, endothelial cells, fibroblasts, cDCs, and pDCs concentrated in tumor tissue, as expected." (PMID 39120585, 2024). "Altogether, these data demonstrate that CCR7+ DCs are critically positioned to regulate anti-tumour cytolytic activity, including via TNF-superfamily ligands such as OX40L, and PVR." (PMID 38267413, 2024). "The results showed that CD200, CD80 and TNFRSF14 were the highest in tumor tissues, CD274 (PDL1), CD86, LGALS9, NECTIN2, PDL2, PVR were lower than those in adjacent tissues but higher than those in normal tissues, and FGL1 was the lowest in tumor tissues." (PMID 39120585, 2024). "Overall, our findings propose PVR and NECTIN2 as promising biomarkers for prognostic assessment and evaluation of immune infiltration across various tumor types, particularly in LGG and ACC." (PMID 39120585, 2024). "It has been demonstrated that CD155, known as the poliovirus receptor (PVR), can interact with receptor CD226 on NK cells to impair NK cell function, thereby inducing tumor immune evasion." (PMID 38596684, 2024). "The extracellular domain (ECD) of the polio virus receptor (PVR; CD155), expressed on antigen presenting cells and tumor cells, is composed of an N-terminal IgV region followed by two IgC elements." (PMID 36944702, 2023). "Originally identified as a poliovirus receptor (PVR), CD155 is involved in various physiological processes, including cell proliferation, adhesion, and potentially tumour invasion and migration." (PMID 37519808, 2023). "This is further supported by the increased expression of the anti-tumor immunity genes PDL1, CD155 (PVR), CEACAM1, LGALS9, and IDO1, all of which antagonize T cell responses via their interaction with inhibitory receptors." (PMID 36680216, 2023). "Lastly, PVR showed the highest expression in the WNT subgroup compared with the subgroups and non-tumor tissue." (PMID 36825029, 2023).
tumor (continued). "TIGIT has two ligands, CD155 (PVR) and CD112 (PVRL2, nectin-2), which are expressed by antigen-presenting cells and tumor cells in TME to decrease the activity of T cells and NK cells." (PMID 37129788, 2023). "However, even though PVR and Nectin2 overexpression represents a danger signal that renders tumor cells susceptible to cytotoxic cell-mediated lysis, several mechanisms—including the increased expression of inhibitory receptors for these ligands—hamper DNAM-1 activation in advanced tumor stages." (PMID 37760586, 2023). "TIGIT is expressed on naïve T cells and activated NK cells and Tregs, and interacts with its two major ligands, poliovirus receptor (PVR; CD155) and poliovirus receptor-related 2 (PVRL2; CD112), which are expressed on myeloid cells and tumour cells." (PMID 37627206, 2023). "Accordingly, monoclonal antibodies inhibit KIR2DL5 interaction with PVR reduced tumor growth in several humanized tumor models, suggesting the blockade of the KIR2DL5/PVR interaction as a novel method of immunotherapy for treating human cancers." (PMID 37760586, 2023). "TIGIT competes with the activator receptor CD226 for the same ligands CD155 (PVR) and CD112 (PVRL2) that are expressed by tumor cells and APCs in the TME." (PMID 37189689, 2023). "In these immunostimulatory marker genes, CD276, MICB, NT5E, PVR and ULBP1 had a significantly positive correlation with RRM2 expression in most tumor types." (PMID 35740608, 2022). "TIGIT has many ligands, CD155 (PVR or Necl-5), CD112 (nectin-2, also known as PRR2 or PVRL2), and CD113, CD155, CD112, CD113, and CD111, which are expressed in APCs or tumor cells." (PMID 35669786, 2022). "TIGIT binds to two ligands, CD155 (PVR) and CD112 (PVRL2, nectin-2), which are expressed by tumour cells and antigen-presenting cells in the tumour microenvironment." (PMID 35057760, 2022). "Anti-MAA T cells have stem-like properties and frequent interactions with regulatory T cells and tumor cells via Galectin9-TIM3 and PVR-TIGIT -axes, respectively." (PMID 36220826, 2022). "In humans, freshly isolated neuroblast susceptibility to lysis directly correlates with the surface expression of CD155 and either DNAM-1 or PVR masking with monoclonal antibodies, resulted in strong inhibition of tumor cell lysis." (PMID 36011052, 2022). "TIGIT also suppresses anti-tumor immunity by TCR downregulation upon the binding to the ligands, CD155 (PVR) and CD112 (Nectin2), expressed in myeloid cells and tumor cells." (PMID 36211375, 2022). "TIGIT binds to two ligands, CD155 (PVR) and CD112 (PVRL2, nectin-2), that are expressed by tumor cells and antigen-presenting cells in the tumor microenvironment." (PMID 35222404, 2022). "As a cell adhesion molecule, poliovirus receptor (PVR/CD155) is abnormally overexpressed in tumour cells, and related to tumour proliferation and invasion." (PMID 35384345, 2022). "The three nectin and NECL molecular family proteins CD155(PVR), CD112(PVRL2 or Nectin-2), and CD113 (Nectin-3), which are expressed on tumor cells or antigen-presenting cells, are the known TIGIT ligands." (PMID 36135216, 2022). "Previous studies have also demonstrated that PVR can regulate the interaction between angiogenesis factor receptor 2 (VEGFR2) and integrin αvβ3, thus promoting the angiogenesis of tumor cells." (PMID 36552960, 2022). "Based on the expression of specific markers, we investigated the relationship between PVR expression and HCC prognosis as well as the level of immune cell in tumor stroma." (PMID 36552960, 2022). "PVR on the tumor cell surface interacts with TIGIT and participates in the formation of an immunosuppressive tumor microenvironment by interacting with co-inhibitory receptors." (PMID 36552960, 2022). "TASCs, DC_LAMP3, and tumor cells, all highly expressed NECTIN2 and PVR (CD155), whose interaction with TIGIT blocks T-cell activation and proliferation." (PMID 35999201, 2022).